HDGF (heparin binding growth factor)
Diseases named in the same sentence as HDGF in open-access papers (continued):
Sharing a sentence is not in itself a finding about the gene and the disease.
tumor (continued). "Mechanistically, IGF2BP3 could serve as an m6A “reader” to recognize m6A modified mRNA and enhance HDGF mRNA stability to promote tumor angiogenesis and glycolysis in GC." (PMID 35986300, 2022). "The Wnt status-dependent, tumor-suppressive role of HDGF knockdown may lead to the urgently needed targeted and personalized HCC therapy." (PMID 35578240, 2022). "Thus, our results suggest that downregulation of HDGF contributes to the tumor-suppressive effects of miR-129-5p by inhibiting ERK1/2 signaling." (PMID 35578240, 2022). "The secreted HDGF promotes tumor angiogenesis by inducing VEGF." (PMID 36561529, 2022). "Also, HDGF is the substrate of and the IGF2BP3, which stabilized HDGF mRNA and subsequently caused tumor angiogenesis." (PMID 35937999, 2022). "HDGF is highly expressed in a variety of cancers, which is—regardless of the tumor type—linked to a negative outcome for patients." (PMID 35578240, 2022). "Since angiogenesis is closely related to tumor metastasis, it can be a novel therapeutic strategy to combine compound C108 with antiangiogenic agents or antibodies against HDGF in the treatment of metastatic ESCC, which may achieve better treatment effects." (PMID 34782720, 2022). "Taken together, these data indicated the significance of HDGF in tumor pathogenesis." (PMID 34774047, 2021). "In addition, m6A modification can also regulate the expression of VEGFA through the miR-143-3P/VASH1 axis, as well as through the regulation of SERPINE2, IL11, and HDGF stability, thus affecting tumor angiogenesis." (PMID 33926508, 2021). "HDGF is involved in tumor-related events such as tumorigenesis, metastasis, and angiogenesis." (PMID 34895232, 2021). "The upregulated HDGF could further facilitate tumor angiogenesis and increase glycolysis in GC, which in turn enhance the tumor growth and liver metastasis." (PMID 33598423, 2020). "In summary, hsa_circ_0079480 is highly expressed in AML and drives by tumor progression via regulation of hsa_circ_0079480/miR-654-3p/HDGF axis, indicating that hsa_circ_0079480 may function as a new treatment target for AML therapy." (PMID 33290265, 2020). "In addition, PTN another gene effected by XIST is a heparin-binding growth factor that is involved with tumour progression." (PMID 33255394, 2020). "Since reversing the overexpression of HDGF inhibited tumor growth in vivo, the reduction of HDGF could be expected to suppress the proliferation of malignant cells, with nominal influence on non-cancerous tissues." (PMID 32545762, 2020). "The expression of HDGF is correlated with tumor mitosis and tumor size." (PMID 32545762, 2020). "Furthermore, hepatoma-derived growth factor (HDGF) and IL-1β promote the secretion by MSCs of pro-tumorigenic cytokines that stimulate tumor progression." (PMID 33114328, 2020). "Furthermore, subcutaneous tumor experiments in nude mice demonstrated that knockdown of HDGF inhibited tumorigenesis, invasion, and metastasis in vivo." (PMID 31032220, 2019). "The mechanism through which HDGF induces or regulates VEGF expression in tumor cells remains unclear." (PMID 31711427, 2019). "Besides the tumor growth, HDGF knock-down decreased the tumor cell migration and invasion in HCT116 cells." (PMID 29568375, 2018). "The function of HDGF in cell survival and tumor formation has been extensively investigated." (PMID 30513684, 2018). "HDGF could be potential target in CAC patients exhibiting increased tumor levels of this protein to improve the clinical outcomes." (PMID 29568375, 2018). "Moreover, histological features of tumor xenograft from NC-siRNA group and HDGF-siRNA group were similar to human CRC tissues by haematoxylin and eosin staining." (PMID 26296979, 2015). "In addition to HDGF, dozens of up-regulated phosphoproteins identified by our platform had dramatic change in expression in the tumour tissue compared to the normal tissue and also passed our criteria since their function is related to cancer." (PMID 29142712, 2015).
tumor (continued). "Apart from the facilitation of EMT, our recent study also suggests that HDGF may promote the cytoskeletal remodelling through stimulation of Rho activity and the formation of podosomes that favours the motility of tumor cells." (PMID 23536873, 2013). "It was found that tumors derived from Ad-HDGF-infected cells had the largest tumor burden." (PMID 23536873, 2013). "Therefore, HDGF overexpression appears to create a favourable environment for tumor progression by promoting tumor proliferation and neovascularisation." (PMID 23536873, 2013). "The proangiogenic activity of bFGF, which is a heparin-binding growth factor, can be inhibited by different strategies, such as the reduction of bFGF production by tumour cells, the modulation of the release of active bFGF from the ECM, and the modification of the FGF-FGFR recognition." (PMID 23737842, 2013). "Nucleolin therefore could possibly serve as the up to now unknown cell surface receptor for HDGF in a GAG-dependent way explaining at least some of its proliferative as well angiogenic properties as an extracellular factor during tumour formation." (PMID 23305559, 2013). "In addition, the role of HDGF in cancer biology has recently become a focus of research, since HDGF was found to be over-expressed in a large number of different tumor types (genecards.org)." (PMID 22217008, 2012). "The correlation between the degree of HDGF overexpression, disease prognosis and the role for HDGF in tumor angiogenesis, metastasis, and apoptosis suggested that HDGF may function as an oncogene/protooncogene." (PMID 22014102, 2011). "In addition, several studies suggested a role for HDGF in tumor angiogenesis, metastasis, and apoptosis." (PMID 22014102, 2011). "HDGF is an index of tumor multiplicity, being a sign of poor prognosis in HCC." (PMID 27942274, 2009). "Importantly, we identified tumour cells of IBC that specifically express the heparin-binding growth factor PTN, the ligand for which is widely expressed in multiple cell types of IBC and the expression scores correlated strongly with the immunosuppressive status of the various cell types." (PMID 40624675, 2025). "Next, we examined whether anti-HDGF antibody can alter the tumor response to osimertinib." (PMID 39041204, 2024). "Furthermore, anti-HDGF antibody could enhance the chemotherapeutic treatment of NSCLC tumor xenografts." (PMID 39041204, 2024). "However, tumor regression occurred in both the HDGF overexpression and control groups, which may be due to the relatively high dosage of gefitinib used in this experiment because PC-9 cells are very sensitive to gefitinib." (PMID 37301856, 2023). "Overexpressed HDGF protein can be secreted and promotes tumor angiogenesis, while nuclear HDGF stimulates the expression of glucose transporter type 4 (GLUT-4) and enolase 2 (ENO2) mRNAs, resulting in increased levels of glycolysis and subsequently causing tumor growth and liver metastasis." (PMID 32404927, 2020). "In addition, HDGF expression was upregulated in tumor tissues, compared with normal tissues." (PMID 33817254, 2020). "However, HDGF siRNA treatment group showed a low increase in tumor volume." (PMID 26296979, 2015). "Our results in combination with previous findings point to a possible role in cell differentiation and suggest that HDGF promotes tumor progression after secondary upregulation and may represent another protein fitting into the concept of non-oncogene addiction of tumor tissue." (PMID 22014102, 2011). "The proto-oncogene heparin-binding growth factor (HDGF) mRNA is methylated by NSUN2, and YBX1 stabilizes HDGF mRNA by binding to m5C methylation sites and recruiting ELAVL1, thereby promoting tumor development." (PMID 40370440, 2025). "Hepatoma-derived growth factor (HDGF) has emerged as a key oncogenic factor in various cancers, promoting tumor growth, angiogenesis, and metastasis." (PMID 41278276, 2025).
tumor (continued). "We discovered that protein modification-related, including HDGF, SIRT-7, UBE2A, and UCHL5, elevated expression in tumor tissues." (PMID 40041484, 2025). "Hepatoma-derived growth factor (HDGF) is also overexpressed in NSCLC, promoting proliferation, migration, and invasion, and is correlated with tumor relapses and poor survival rates." (PMID 41440381, 2025). "Concurrent inhibition of HDGF with the initiation of TKI treatment can re-sensitize drug-tolerant cells to TKI, resulting in enhanced tumor regression and delayed disease progression." (PMID 39041204, 2024). "For exerting its function, METTL3 enhanced HDGF mRNA stability, then HDGF activates GLUT4 and ENO2 expression to increase glycolysis, accompanied by tumor growth and metastasis to liver." (PMID 38075202, 2024). "IGF2BP3, as the m6A reader, directly recognized and bound with the m6A site of HDGF mRNA stability mediated by elevated METTL3 expression, which are correlated with tumor angiogenesis and liver metastasis by maintaining HDGF mRNA stability." (PMID 39009956, 2024). "Upregulated NAP1L1 plays a pro-tumorigenic role by recruiting HDGF to interact with c-Jun, thereby upregulating the expression of CCND1 and promoting the proliferation of tumour cells." (PMID 38538582, 2024). "Upregulated NAP1L1 increases the expression of the cell cycle protein cyclin D1 (CCND1) by recruiting heparin-binding growth factor (HDGF) and interacting with c-Jun, thereby enhancing the proliferation of HCC cells and promoting tumour progression." (PMID 38538582, 2024). "It was reported that METTL3 regulates HDGF in an m6A-mediated manner to promote tumor angiogenesis and glycolysis and also regulates ZMYM1, SPHK2, and MYC to promote GC tumor metastasis." (PMID 39195675, 2024). "HDGF was increased by gefitinib administration in PC-9 xenograft tumors with HDGF overexpression (P < 0.05), and other changes in HDGF and p-EGFR in tumor tissues were consistent with the cell experiments." (PMID 37301856, 2023). "Tumor angiogenesis is promoted by the secretion of HDGF, whereas the activation of GLUT4 and ENO2 expression by nuclear HDGF leads to an increase in glycolysis in GC cells." (PMID 38201270, 2023). "Next, we found that the levels of p-EGFR were inversely correlated with HDGF knockdown or overexpression in NSCLC cells and tumor tissues." (PMID 37301856, 2023). "These outcomes revealed a suppressive role of circ-IARS knockdown in tumor growth of NSCLC in vivo via regulating miR-1252-5p and HDGF." (PMID 36694627, 2023). "Mechanistic studies showed that LINC00958 targeted miR-3619-5p to utilize its tumor promoting effects in HCC, and hepatoma-derived growth factor (HDGF), a direct target of miR-3619-5p, was also vital for the function of LINC00958." (PMID 37069649, 2023). "Paired tissues were recruited from 44 NSCLC patients, and circ-IARS and HDGF were upregulated, while miR-1252-5p was downregulated in NSCLC tumor tissues." (PMID 36694627, 2023). "In contrast, silencing HDGF by CRISPR inhibited the malignant phenotype of H1975 cells and retarded tumor development in vivo." (PMID 37301856, 2023). "HDGF promotes the expression of GLUT and ENO2 in the nucleus and initiates the glycolytic pathway in tumor cells." (PMID 36561529, 2022). "Secreted HDGF facilitated tumor angiogenesis, while nuclear HDGF stimulated ENO2 and GLUT4 expression, followed by increased GC cell glycolysis, promoting tumor growth and metastasis." (PMID 35711459, 2022). "Together, these results showed that pair-wise genetic perturbation of HDGF and LGR5 with the addition of MAPKi efficiently disrupted the formation of tumor spheroids in the 3D growth environment." (PMID 34106558, 2021). "Many cytokines, such as HDGF, TGF-β, FGF2 and G3BP1, which are validated tumor promoters, participate in cell migration and metastasis induced by the m5C modification, indicating a strong correlation between the RNA m5C level and mobility of cancer cells." (PMID 34512153, 2021).
tumor (continued). "Concerning the genes related to tumor progression, we found HSP90AB1, GRB2, ERBB2/3, EIF4A3, HDGF, and CSNK2B." (PMID 25625699, 2015). "HDGF and β-catenin protein expressions were higher in CRC cell lines including HT29, SW116, HCT116, and LOVO compared with non-tumor colorectal mucosa (ANM) by Western blot analysis, respectively." (PMID 26296979, 2015). "Thus, HDGF derived from tumors may promote tumor growth and angiogenesis via paracrine mechanisms." (PMID 24692842, 2014). "Hepatoma-derived growth factor (HDGF), a promoter of tumor angiogenesis, is a downstream target of miR-214 that is downregulated in HCC." (PMID 23431261, 2013). "In this dataset, all the 7-gene candidates exhibited a significant increase of mRNA expression in the metastasis group relative to localised tumours, with RUVBL1 exhibiting near statistical significance (U2AF2 P = 0.0106, RUVBL1 P = 0.051, HDGF P < 0.0001, FABP4 P = 0.0005, and STMN1 P = 0.032)." (PMID 39402324, 2024). "Furthermore, HDGF and EGFR have complementary roles in maintaining the survival of tumor cells exposed to gefitinib." (PMID 37301856, 2023). "Moreover, circ-IARS expression was reduced by 62.00% in xenograft tumor tissues than in the sh-circ-IARS group, which was accompanied by 2.89-fold upregulation of miR-1252-5p and 65.00% downregulation of HDGF." (PMID 36694627, 2023). "Because HDGF is a secretory protein, we detected its concentrations in the plasma of NSCLC tumor-bearing mice to explore whether plasma HDGF levels are relevant to gefitinib efficacy." (PMID 37301856, 2023). "Mechanistically, m6A modification enhanced the expression of hepatoma-derived growth factor (HDGF), which could activate solute carrier family 2 member 4 (GLUT4) and enolase 2 (ENO2) to potentiate aerobic glycolysis in tumor cells." (PMID 33879256, 2021). "We also found that HDGF and LGR5 co-localized morphologically in the microvasculature regions, suggesting that HDGF and LGR5 might both be involved in tumor angiogenesis and cancer stemness." (PMID 34106558, 2021). "Specifically, elevated m6A level of HDGF mRNA promoted its stability via the binding of IGF2BP3, and the upregulated HDGF activated GLUT4 and ENO2 expression to promote glycolysis and eventually tumor growth and metastasis of GC cells." (PMID 32854717, 2020). "IPA-derived relational networks reflect the possible roles of known oncogenes, e.g., MYC and HDGF (REF: PMID 27543492), overexpressed in B-raf V600E_high samples, and tumor suppressors, e.g., PML and toll-like receptors (PMID: 30127747, 29416846), downregulated in B-raf V600E_high samples." (PMID 31835364, 2019). "Conversely, proteins that were significantly more abundant in the B-raf V600E_high samples were clearly related to the proliferative nature of these tumors (and poor prognosis) and include several known oncogenes tumor drivers, e.g., the transcription factor MYC, and the growth factor HDGF." (PMID 31835364, 2019). "PEAR1 interactions with HDGF and PRCC might modulate their cancer-related role and open up for future research of PEAR1 in the tumour biology field." (PMID 29614055, 2018). "To determine whether HDGF affects the tumorigenicity of CRC cells in vivo, we performed tumor growth experiments in nude mice using HT29 cells." (PMID 26296979, 2015). "ECM1 is known to interact with the EGF domain on other proteins, such as perlecan, and perlecan may induce heparin-binding growth factor responses, including the fibroblast growth factor 2 (FGF2) response, and thereby promote tumor growth." (PMID 25499743, 2014). "So HDGF can play a role in the tumorigenesis and tumor progression of EFST, but it shows no prognostic value." (PMID 19144156, 2009). "Heparin-binding growth factor (PTN)-secreting tubulointerstitial-like progenitor cells are more enriched in IBC patients and can mediate the proliferation of immature perivascular cells via the NRP1 receptor, thereby promoting the invasion and metastasis of IBC tumour cells." (PMID 40624675, 2025).
tumor (continued). "HDGF released by tumor cells could signal to the nonmalignant cells in the tumor microenvironment to promote the survival and malignancy of tumor cells." (PMID 39041204, 2024). "In addition, we did not observe significant changes in HDGF staining intensity in Western blot analysis of tumor proteins extracted from different treatment arms." (PMID 39041204, 2024). "Altogether, these results indicate that HDGF potent induces ROS generation may involve in tumorigenicity in not only tumor cells but also nontransform cells." (PMID 37827291, 2023). "Interestingly, hepatocyte growth factor (HGF) induced HDGF in a dose-dependent manner, and HDGF induced the expression of VEGF, thus suggesting that HDGF may be involved in tumor growth by means of its cooperation with these growth factors." (PMID 32545762, 2020). "Blood vessels support GSCs; these tumor cells in turn may regulate and contribute to the tumor vasculature, by directly transdifferentiating into endothelial cells or through the secretion of regulatory growth factors such as VEGF and hepatoma-derived growth factor (HDGF)." (PMID 35057010, 2022). "HDGF has mitogenic, angiogenic, neurotrophic and antiapoptotic activity but the molecular mechanisms by which it exerts these activities are largely unknown nor has its biological function in tumours been elucidated." (PMID 23305559, 2013). "Therefore, HDGF may represent another protein fitting into the concept of non-oncogene addiction of tumor tissue, supporting the assumption of other research groups that HDGF could serve as a target for cancer drug development." (PMID 22014102, 2011). "In primary HGSOC, the recurrent tumor-specific DEG IL7R exhibited a positive correlation with AMBP and HDGF and a negative correlation with FEN1, LRRC25, RIGI, and TBL1X (p < 0.05)." (PMID 41596598, 2026). "Immunohistochemical analysis and dihydroethidium (DHE) staining showed that HDGF expression and DHE fluorescence staining were significantly higher in tumor regions than in adjacent nontumor regions." (PMID 37827291, 2023).